MMP2 (matrix metallopeptidase 2)
Diseases named in the same sentence as MMP2 in open-access papers (continued):
Sharing a sentence is not in itself a finding about the gene and the disease.
tumor (continued). "In addition to MMP-2, MMP-9 has been extensively reported to promote tumor invasion and metastasis in CRC and other malignancies, while also playing a role in immune regulation." (PMID 40611940, 2025). "Hence, upregulating the gene by blocking the IGF complex favors tumor suppression and is also a sign of activity accelerating proteolysis of two proteinase genes (PAPPA and MMP2)." (PMID 39854135, 2025). "By targeting tumour cells through HER2 and releasing the MMP2/MMP9 inhibitor at specific sites within the tumour microenvironment, we could achieve reduced adverse events and enhanced therapeutic impact." (PMID 40259907, 2025). "Decreased miR-138 expression also increases MMP-2 and MMP-9, promoting tumor metastasis." (PMID 41356146, 2025). "Additionally, CD133 activation initiates the MAPK pathway, increasing MMP-2, MMP-9, and VEGF expression, thereby promoting angiogenesis and tumor development." (PMID 40399946, 2025). "MMP-2 and MMP-9 degrade type IV collagen, increasing the availability of angiogenic factors, and promoting tumor angiogenesis, which provides nutrients and oxygen to tumor cells." (PMID 39911388, 2025). "Thus, NORAD knockdown in HNSCC-derived tumor stem cells attenuates migration and invasion, lowers the expression levels of EMT-related markers, like MMP2, MMP9, N-cadherin, and vimentin, and upregulates E-cadherin expression." (PMID 41020820, 2025). "Additionally, sesamin inhibits MMP2 expression by downregulating the STAT3 signaling pathway, leading to reduced tumor cell migration, invasion, and anoikis resistance." (PMID 40303286, 2025). "Non-coding RNAs reciprocally regulate FN1: tumor-suppressive hsa_circ_0050386 binds SRSF3 to block FN1 pre-mRNA splicing and suppress metastasis, while oncogenic Lnc-PDZD7-3 upregulates FN1 to enhance MMP2/9-mediated invasion." (PMID 41301482, 2025). "In addition, matrix metalloproteinases (MMP-2, MMP-9, and MT1-MMP) have been identified in papillary myxomas, contributing to ECM degradation, tumor fragility, and inflammation-driven remodeling." (PMID 41376733, 2025). "Additionally, they control the activity of Matrix Metallopeptidase-2 (MMP-2), MMP-9, MMP-11 and plasmin, which impacts the disintegration of the extracellular matrix, a crucial requirement for tumour invasion and metastasis." (PMID 40270992, 2025). "To validate the tumor‐specific accumulation of PreS1‐pHLIP NMs in response to MMP2, we developed a fluorescence probe encapsulating Cyanine 5.5 (Cy5.5) and the BHQ3 quencher within the nanomaterials to monitor MMP2‐triggered disassembly in vivo." (PMID 40091501, 2025). "Vimentin and N‐cadherin are key markers of the epithelial–mesenchymal transition (EMT), a process that enhances cell motility and invasiveness, while MMP2 and MMP9 are matrix metalloproteinases involved in the degradation of the extracellular matrix, facilitating tumour invasion and metastasis." (PMID 40794013, 2025). "The overexpression of miR-124, which functions as a tumor suppressor in BC, markedly inhibits the expression of angiogenesis markers including VEGF, MMP-2, and MMP-9, thereby suppressing the migration, invasion, and angiogenesis of BC cells in vitro, as well as tumor growth in vivo." (PMID 39981244, 2025). "Nevertheless, the observed increase in MMP-2 and MMP-9 expression in CAR-T cells may contribute to their migration from the tumor vasculature, highlighting their additional therapeutic role." (PMID 40666525, 2025). "Additionally, MMP-2 and MMP-9 facilitate tumor invasion and angiogenesis through the proteolytic activation of TGF-β." (PMID 41153831, 2025). "The dynamic modulation of stealth properties arises from the engineered liposomes’ dual functionality: exploiting PEG for prolonged blood circulation, followed by MMP-2-triggered cleavage of the GPLGVRG peptide, resulted in selective PEG5K shedding within tumor microenvironments." (PMID 40732329, 2025).
tumor (continued). "MMP-2 and MMP-9 degrade key ECM components—such as collagen IV, laminin, and fibronectin—facilitating basement membrane disruption, increased matrix porosity, and enhanced tumor invasion." (PMID 40906383, 2025). "In another study, MMP-2/9-sensitive micelles demonstrated improved tumour targeting and accumulation compared to nonsensitive micelles in vivo, due to specific release of cargo at the tumour site." (PMID 40867257, 2025). "In addition, primary tumor-derived signals upregulate MMP9 and MMP2 in hepatic sinusoidal lining cells." (PMID 41463352, 2025). "These include ECM proteins like collagen, MMPs (MMP-2, -9, and -13), angiogenesis-related factors (VEGF), growth factors (TGF-β, HGF), and chemokines such as CXCL-8 and IL-6, which affect tumor cell growth, metastatic potential, drug resistance, and CSC self-renewal." (PMID 40399946, 2025). "TGF-β assists MMP-2 and MMP-9 promote tumor growth and metastasis." (PMID 40563423, 2025). "Moreover, a matrix metalloproteinase-2 (MMP-2)-cleavable linker of seven peptides, GPLGLAG, has been inserted to achieve tumor-specific infiltration and enhance the uptake of the polymer." (PMID 41012497, 2025). "Additionally, migration assays and gelatin zymography demonstrated that the analogs, unlike vemurafenib, significantly inhibited matrix metalloproteinases MMP-2 and MMP-9, key enzymes involved in tumor invasion and metastasis." (PMID 40872552, 2025). "ZnO-LD NPs displayed deep tumor penetration and significant ROS-mediated apoptosis in 3D cultures of PC-3M and 4T1 cells, while ZnO/DPPG/PEG-pp-PE/DOX nanoparticles enhanced spheroid penetration following MMP2 activation." (PMID 40943339, 2025). "Matrix metalloproteinase-2 (MMP-2), traditionally known for its role in tumor invasion, metastasis, and angiogenesis, has not been thoroughly investigated in the relationship to immunotherapy for COAD." (PMID 40611940, 2025). "Additionally, M2-polarized TAMs secrete matrix-remodeling enzymes such as MMP-2, which facilitate tumor dissemination, while their production of IL-10 suppresses pro-inflammatory cytokines (TNF-α, IL-12, IL-1) and promotes tumor immune escape." (PMID 41394845, 2025). "Metalloproteinase ADAM15 and MMP2 were expressed in tumor-like cells and tumor spheres to some extent but notably absent in normal organoids and organoid slices." (PMID 40917877, 2025). "In contrast, SP abundance did not correlate significantly with MMP-2 expression across tumor stages (p > 0.05)." (PMID 40321254, 2025). "In the process of acquiring the M2 phenotype, GAMs secrete immunomodulatory and tumor-promoting factors such as TGF-β, epidermal growth factor (EGF), IL-10, and the proteolytic enzymes MMP-2 and MMP-9, thereby reinforcing an immunosuppressive tumor milieu within the glioblastoma microenvironment." (PMID 41479886, 2025). "The anti-tumor effect of BV components may result from reducing the secretion of MMP-2 and MMP-9 into the extracellular space, thus reducing the potential ability to degrade the tissue surrounding the tumor." (PMID 40141020, 2025). "It has been proposed that HSP90 activates CSC mechanisms which upregulate the expression of MMP-2 and MMP-9 and that interaction with secreted MMPs induces local degradation of the extracellular matrix and enhances tumor cells migration, especially those with the CSC phenotype." (PMID 41369386, 2025). "Molecular docking simulations were performed to analyze the binding affinities of these agents to MMP2 and MMP9, alongside scratch assays and gene expression analysis to assess their inhibitory effects on these key enzymes involved in tumor invasion and cell migration." (PMID 40136519, 2025). "Furthermore, STAM2 significantly influences the expression of MMP2/MMP9, as well as the phosphorylation of JAK2/STAT3 in cancer cells, thereby enhancing tumor malignancy." (PMID 40149859, 2025). "MMPs, specifically MMP-2 and MMP-9, facilitate angiogenesis, tumor growth, and cancer spread." (PMID 41179937, 2025).
tumor (continued). "MMP2 and MMP9 are known to induce the dissemination of tumor cells." (PMID 40566630, 2025). "Additionally, it inhibits proteasome activity, DNA methyltransferases, and matrix metalloproteinases (MMP-2 and MMP-9), thereby suppressing tumor progression, invasion, and the epigenetic silencing of tumor suppressor genes." (PMID 40871008, 2025). "Additionally, TAMs release matrix metalloproteinases (MMP2 and MMP9), which degrade the extracellular matrix (ECM) and facilitate tumor cell invasion and migration." (PMID 40104956, 2025). "In fact, no direct evidence supports a requirement for MMP2 or other MMPs in eHsp90α-stimulated tumor cell migration or invasion." (PMID 41440009, 2025). "Additionally, M2d-polarized macrophages stimulated by adenosine, IL-6 and tumor cells secrete proteases (such as MMP-2), cytokines (such as VEGF) and anti-inflammatory factors (such as TGF-β and IL-10) to promote angiogenesis and tumor immunosuppression." (PMID 40703527, 2025). "CuS@mSiO2-PEG photothermal nanoparticles reduced HeLa cell metastasis and enhanced survival in tumor-bearing mice by downregulating MMP-2/9 and inhibiting the non-receptor tyrosine kinase/focal adhesion kinase pathway." (PMID 40284474, 2025). "CD44, MMP-2, MMP-9, N-cadherin, and ZEB-2 were selected because they complementarily represent the three main axes of early tumor invasion: cell adhesion (CD44 and N-cadherin), extracellular matrix degradation (MMP-2 and MMP-9), and epithelial–mesenchymal transition (N-cadherin)." (PMID 40940940, 2025). "MMP-2 and MMP-9 facilitate angiogenesis, which is critical for tumor growth beyond a certain size by providing necessary nutrients and oxygen; these enzymes do this by breaking down the ECM components around blood vessels, thus allowing endothelial cells to migrate and form new blood vessels." (PMID 39858430, 2024). "Furthermore, the expression of MMP2 and MMP9 in 4T1 tumor tissue was investigated, with immunohistochemical findings indicating a correlation with COX‐2 expression." (PMID 39554336, 2024). "Notably, numerous studies have demonstrated that MMP-2 and MMP-9 inhibition undermines tumor metastasis capability." (PMID 39063556, 2024). "Another study found that Per1 knockout increased the expression of MMP9 and MMP2 and also reduced the expression of TIMP-2, which may lead to the observed increase in tumor cell invasion and migration." (PMID 38903177, 2024). "Expression of MMP-9 in tumor tissue was significantly upregulated (increased of 242%, p = 0.0107) as opposed to the almost identical expression of MMP-2 (p = 0.9245;)." (PMID 38275897, 2024). "Up-regulated the expression of IL-8, MMP2, MMP9, p-STAT3, and ZEB1 in tumor." (PMID 39906741, 2024). "Particularly, MMP-2 and MMP-9 are MMPs overexpressed in GBM that are involved in tumor progression." (PMID 38732135, 2024). "Therefore, the role of MMP-2 and MMP-9 is considered to be one of the key steps in tumor metastasis." (PMID 38776295, 2024). "To ensure that miR-4488, RTN3, and FABP5 do not independently affect the expression of MMP2 in tumor cells, we conducted Western blot experiments." (PMID 38904015, 2024). "The MMP-2 expression in all groups was not changed, suggesting the underlying mechanism of CRC tumor invasiveness is extremely intricate." (PMID 38256960, 2024). "Concerning tumor progression, the steroid sapogenin diosgenin reduced the migration and invasion capabilities of PC3 cells, inhibiting the expression and activation of MMP-2, MMP-7, and MMP-9, which have a crucial role in extracellular matrix degradation." (PMID 39200101, 2024). "These activated CAFs in turn promote tumor progression by secreting angiogenetic cytokines and EMT regulators, such as vascular endothelial growth factor (VEGF), matrix metalloproteinase 2 (MMP2), MMP9, basic fibroblast growth factor (bFGF), and transforming growth factor beta (TGF-beta)." (PMID 38339318, 2024). "MMP2 and MMP9 are often overexpressed in cancers and promote tumor metastasis." (PMID 38430256, 2024).
tumor (continued). "Notably, MMP-9 and MMP-2 are key contributors, as they proteolytically cleave and activate latent transforming growth factor-beta (TGF-β), thereby promoting tumor angiogenesis." (PMID 38672182, 2024). "PSTAG reduces the interaction of BiTE with nontumor cells and thereby improves its half-life, whereas PLGLAG, when cleaved by matrix metalloproteinase-2 (MMP2), augments the BiTE core to bind PD-L1 and CD3 in the tumor microenvironment and exerts its antitumor activity." (PMID 39156005, 2024). "Elevated MMP2 expression is correlated with advanced CRC and aggressive tumor characteristics." (PMID 38978899, 2024). "Indeed, the treatment of leukemic cells with the specific inhibitor CP1B, derived from calpastatin, affects the expression and secretion of MMP-2/MMP-9, reducing matrix degradation and thus tumor invasion." (PMID 39156707, 2024). "Notably, additional ECM invasion-related proteases, including MMP2, 9, 13 and PLAU, were also reduced, to varying degrees, in siSE-LbL-treated tumor nodules." (PMID 38437557, 2024). "Given the crucial role of MMP-2 and MMP-9 in tumor migration and invasion, research has substantiated that inhibiting the MAPK (JNK/P38/ERK) pathway and reducing MMP-2, MMP-9, and uPA protein expression can effectively prevent cancer cell migration and invasion." (PMID 38374934, 2024). "In our study, plasma MMP-2 concentrations were slightly higher in patients with benign lesions (BL) compared to OC patients, but this was not a statistically significant difference (BL—median: 211 ng/mL; OC—median: 203 ng/mL)." (PMID 38892452, 2024). "It was shown that some of the studied compounds, along with inhibition of the expression of key genes of the Hh signaling pathway, also reduced the expression of MMP-2 and MMP-9, which should have a general inhibitory effect on the development of the tumor process." (PMID 39274874, 2024). "The concordant changes in protein expression results with the values detected at the gene expression can be observed in all the evaluated parameters of integrin αV, brevican, CSPG-5, versican, integrin β-5, and CD44 and only in tumor staining in the case of MDM2, MMP2, and FLT-4." (PMID 39595920, 2024). "In a study on tumor disease, it was also found that IL-33 may activate the ST2-NF-κB signaling pathway, increasing the expression of MMP-2 and MMP-9." (PMID 39172956, 2024). "Additionally, the expression of matrix metalloproteinase (MMP)-2 and MMP-9 in tumor cells was decreased after DON treatment." (PMID 38386265, 2024). "In vitro experiments further substantiate these findings, as ADM knockout inhibits proliferation, migration, and invasion of OSCC cells, reduces mRNA levels of MMP2, and induces compensatory upregulation of RAMP2, therefore suppressing tumor cell migration and invasion." (PMID 38256104, 2024). "Overexpression of MMP2 and 9, which can proteolytically cleave the epithelial markers E‐cadherin, has been correlated to the induction of EMT as well as increased invasion of tumor cells." (PMID 39092293, 2024). "Moreover, miR-21 stimulates epithelial–mesenchymal transition (EMT) and upregulates the expression of matrix metalloproteinase-2 (MMP-2) and matrix metalloproteinase-9 (MMP-9), promoting tumor metastasis." (PMID 38473877, 2024). "The presented results indicate the significant correlation between the CXCL12, CXCR4, CXCL8/CXCR2, M-CSF, MMP-2, MMP-9 ADAM17, ADAMTS-6, and CLDN7 levels and tumor stage, as well as the clinicopathological parameters of OC, such as the presence of lymph node and/or distant metastases." (PMID 38673838, 2024). "Hence, we evaluated the expression of MMP2 and MMP9 to further explore the molecular mechanism by which the 3D microenvironment in the MC-B hydrogels regulates tumor aggressiveness in PC." (PMID 39057404, 2024).
tumor (continued). "Co-culturing with PDSS2-Del2 overexpressed HCC cells stimulates the PI3K/AKT signaling pathway in macrophages, promotes macrophage differentiation towards the M2 type, and induces MMP2/MMP9 secretion, thereby providing a suitable microenvironment for tumor metastasis." (PMID 39695147, 2024). "Monitoring levels of MMP-2 and MMP-9 in patients could serve as a biomarker to assess the aggressiveness of the tumor, predict prognosis, or evaluate the effectiveness of gelatinase inhibitors as part of the treatment regimen." (PMID 39858430, 2024). "Genistein did not have any clear effect on MMP-2 when applied alone, probably due to the rather low dose used, but halved its mRNA expression in tumor sections when administered together with cisplatin." (PMID 39335164, 2024). "DI/Pep1 is cleaved by MMP‐2 in the TME and transforms into aggregates with a high aspect ratio, thus controlling the drug release rate and prolonging the retention time of the drug in tumor tissues and enhancing site specificity and efficacy." (PMID 39545088, 2024). "OPN is a tumour-microenvironment (TME) component that is actively secreted by tumour cells and plays a pivotal role in the progression of cancer cells by upregulating MMP2/9, VEGF, and other key factors." (PMID 39275349, 2024). "Specific MMPs, including MMP2, MMP9, MMP11, MMP14, MMP15, MMP25, and MMP28, were increased in this region, indicating their distinct roles in the tumor microenvironment and confirming the importance of understanding the effects of cysteamine on specific MMPs in GBM cancer models." (PMID 38893149, 2024). "The remodeling of the ECM by MMP-2 and MMP-9 can also modulate the local immune response, potentially aiding the tumor in evading immune surveillance and changes in the ECM can influence the infiltration and activity of immune cells in the tumor microenvironment." (PMID 39858430, 2024). "In contrast to other macrophages, TAMs have specific receptors and ligands; for example, TAM can enhance phagocytosis by binding to extracellular matrix metalloproteinase ligands (e.g., MMP-2, MMP-7, MMP-9, and MMP-12), which in turn promotes tumor growth and metastasis." (PMID 38806553, 2024). "Additionally, we observed upregulation of IL-1β target genes IL-8, VEGF, CCL5, and MMP2 in SUM159, MCF12A and MDA-MB-231 cells This upregulation indicates functional activation of IL-1β signaling in tumor cells co-cultured with B cells." (PMID 39801513, 2024). "Additionally, our immunofluorescence assay of subcutaneous tumor tissues indicated that ZSTK474 effectively suppressed the expressions of vascular endothelial growth factor VEGF and matrix metalloproteinases MMP2 and MMP9." (PMID 39466763, 2024). "Interestingly, the elevated expression of MMP1, MMP2, and MMP3 observed in 3D CAF monocultures was downregulated in 3D co-cultures, indicating a tumor-mediated suppressive effect on these genes." (PMID 39700125, 2024). "Additionally, tumor samples from PAR-1 siRNA-treated mice showed a decrease in blood vessel density and VEGF, IL-8, and MMP-2 expression levels in comparison to control animals." (PMID 38791873, 2024). "The tumor cells invading the surrounding tissue in SW480 and HT-29 xenografts were evaluated by morphological features using H&E staining and the expression of matrix metaloprotease-2 and -9 (MMP2 and MMP9) on the tumor slices." (PMID 38256960, 2024). "Studies have shown that CUR inhibits tumor generation, proliferation, and metastasis by downregulating cyclin B1, activating the caspase-9/3 cascade, inhibiting the PI3K/Akt/mTOR signaling pathway, and suppressing matrix metalloproteinase-2 (MMP-2)." (PMID 38910887, 2024). "Taking together, it is evident that nimbolide inhibits tumor cell growth and migration by downregulating VEGF-A and MMP-2/9 expression, through the inhibition of ERK1/2, and by reducing nuclear translocations as well as the DNA-binding activities of NF-κB in cancer cells." (PMID 38571915, 2024).